TNFRSF9 (TNF receptor superfamily member 9)
Diseases named in the same sentence as TNFRSF9 in open-access papers (continued):
Sharing a sentence is not in itself a finding about the gene and the disease.
keloid (1 paper, 2026). An irregularly shaped, elevated mark on the skin caused by deposits of excessive amounts of collagen during wound healing. "AMPH and TNFRSF9 are promising diagnostic biomarkers for keloid, while quercetin from Aloe vera targets HAS2 and IL6, offering therapeutic potential." (PMID 41544047, 2026). "Nonetheless, this outcome underscores the strong discriminatory potential of TNFRSF9 in keloid pathogenesis within the constraints of the current dataset." (PMID 41544047, 2026). "While both genes showed elevated expression in keloids (log2FC > 1), only TNFRSF9 reached statistical significance (p = 0.0091 vs p = 0.1 for AMPH) in the testing cohort GSE44270 (n = 12; 9 keloid and 3 normal)." (PMID 41544047, 2026). "Through machine learning-based feature selection, two feature genes—AMPH (Amphiphysin) and TNFRSF9 (Tumor Necrosis Factor Receptor Superfamily Member 9)—were identified as potential keloid biomarkers." (PMID 41544047, 2026). "Future studies should prioritize experimental validation of AMPH/TNFRSF9 in larger cohorts, functional characterization of IL6/HAS2 in keloid models and development of quercetin topical formulations to address the clinical need for safe and effective anti-keloid treatment." (PMID 41544047, 2026).
medulloblastoma (1 paper, 2025). A malignant, invasive embryonal neoplasm arising from the cerebellum. "Performing a five-year survival analysis on clinical and gene expression data for 375 medulloblastoma patients, we observe high TNF-alpha expression to be significantly correlated with worse survival and high TNFRSF9 expression to be significantly correlated with improved survival." (PMID 40240536, 2025).
myxoid liposarcoma (1 paper, 2022). A liposarcoma characterized by the presence of round non-lipogenic primitive mesenchymal cells and small signet ring lipoblasts within a myxoid stoma with a branching vascular pattern. "Differential gene expression between radioresponsive myxoid liposarcoma (MLPS) and more radioresistant undifferentiated pleomorphic sarcoma (UPS) indicated UPS contained higher transcript levels of a number of immunotherapy targets (CD73/NT5E, CD39/ENTPD1, CD25/IL2RA, and 4–1BB/TNFRSF9)." (PMID 35558159, 2022).
pneumonia (1 paper, 2022). An acute, acute and chronic, or chronic inflammation focally or diffusely affecting the lung parenchyma, caused by an infection in one or both of the lungs (by bacteria, viruses, fungi, or mycoplasma.). "Nevertheless, several of them, SELL, GZMB, and CCR7 (at 3 dpi), and HAVCR2 (TIM-3), TNFRSF9 (CD137), and GPR18 (at 6 dpi) were promptly upregulated for the virulent Lena strain, probably associated with the marked clinical signs, the earlier and stronger peak of replication, and severe pneumonia." (PMID 34851149, 2022).
steatosis (1 paper, 2022). Increased lipid within the cytoplasm of cells. "We found that the plasma level of TNFRSF9 was significantly lower in all three steatosis groups versus no steatosis." (PMID 35128832, 2022).
tumor (809 papers, 2009 to 2026). "In the scRNA-seq datasets, we confirmed that effector-like CD8POS T cells at the tumor site can express TNFRSF9 (encoding for 4–1BB)." (PMID 40842154, 2025). "In contrast, tumor-associated samples (gene sets 3 and 4) contained upregulated inflammation-related genes (Tnfrsf9, Fasl, Ccr5) and purinergic pathway genes (CD38, P2rx7)." (PMID 41279375, 2025). "Inhibitory immune marker (HAVCR2) and activating immune receptors (CD80, TNFRSF4, and TNFRSF9) were both at higher levels in the high-risk group, suggesting a complex immune microenvironment within the tumor." (PMID 33850474, 2021). "TNFRSF9 plays a specific role in tumor metastasis, which consists in stimulating the immune system, but is simultaneously associated with tumor metastasis; the reason for the occurrence of this phenomenon remains unclear." (PMID 34367975, 2021). "On one hand, TNFRSF9 can augment CD8 + T cell-mediated tumor-related immune responses by boosting the immune functions of CD4 + T and NK cells." (PMID 40072746, 2025). "Currently, monoclonal antibodies against TNFRSF9 have been extensively tested in several tumor-related clinical trials." (PMID 40599317, 2025). "In combination with PD-L1, TNFRSF9 enhances tumour control by effectively activating and expanding the ability of specific cytotoxic T cells to target and eliminate tumour cells." (PMID 40181975, 2025). "If tumor cells exhibit high expression of TNFRSF9, the body's ability to kill these tumor cells will be stronger." (PMID 40072746, 2025). "Compared to Treg.1, Treg. showed significantly up-regulated genes (TNFRSF4/OX40, TNFRSF18/GITR, TNFRSF9/4–1BB, TNFRSF1B/TNFR2 and LAIR2) associated with suppressive functions of tumor-infiltrating Tregs49." (PMID 39803458, 2025). "In our investigation of pseudotime gene expression patterns within the PTPN family, we found that elevated expression levels were predominantly present in TNFRSF9+ regulatory T cells (Tregs), CD8+ TEMRA cells, and M2 tumor-associated macrophages (TAMs)." (PMID 40570022, 2025). "Further analysis of marker gene expression revealed that Tfh and Treg cells in the low AA group expressed higher levels of markers characteristic of IFNG+ Tfh cells and TNFRSF9+ Treg cells, which are identified as key tumor-reactive subclusters." (PMID 40475762, 2025). "Pancancer analysis revealed that TNFRSF9+ Tregs exert potent immunosuppressive effects in the tumor microenvironment across multiple cancer types, but there are still questions regarding their origin and regulatory factors." (PMID 39783838, 2025). "The elevated expression of PTPN family members within TNFRSF9+ Tregs suggests their substantial influence on the behavior of these immunosuppressive cells within the tumor microenvironment." (PMID 40570022, 2025). "Mouse tumor models have proven that TNFRSF9 enhances anti-tumor immune responses by strengthening the functionality of CD4+ T cell, thereby amplifying the effectiveness of CD8+ T cell-mediated responses." (PMID 39232806, 2024). "This was also accompanied by the upregulation of proliferation marker MKI67, costimulatory genes (CD28, TNFRSF9 (4-1BB), and tumor-reactivity markers (e.g., ENTPD1/CD39, ITGAE/CD103) suggestive of an anti-tumor response in face of rising tumor levels." (PMID 37919606, 2024). "ITGA5 and SLC7A1 were found to be overexpressed in CC tumor tissues and were associated with a worse prognosis, except for LCK, GCH1 and TNFRSF9." (PMID 38903179, 2024). "TNFRSF9, also known as 4-1BB, is reportedly expressed in both mouse and human tumor-infiltrating regulatory T cells (TI-Tregs)." (PMID 38903179, 2024). "The transcriptomic profile that we found in tumour-reactive CD137+ CD8+ T cells suggested an exhausted/activated-like phenotype with increased expression of TNFRSF9, LAG3, PDCD1, TIGIT and HLA-DPA1/HLA-DQA1." (PMID 38986249, 2024). "Among these, IL2RA and TNFRSF9 have been previously established as functional markers for tumor-infiltrating Treg." (PMID 38887516, 2024).
tumor (continued). "HVJ-E + anti-4-1BB agonist antibody, another T cell costimulatory molecule known as Tnfrsf9 or Cd137, showed similar tumor growth suppression." (PMID 39534532, 2024). "TNFRSF9 is expressed on the surface of antigen-presenting cells, such as Mø and B cells, as well as various tumor cells." (PMID 38835752, 2024). "Our results revealed that sCD137 levels were significantly elevated in OS patients, and TNFRSF9 expression was also significantly elevated in OS tumor tissue." (PMID 38730580, 2024). "The investigation aimed to elucidate the potential impact of CD47 interaction with TNFRSF9 within the tumor immune microenvironment (TIME) on CD8 + T cell functionality and its consequent effect on the prognosis of patients with malignant tumors." (PMID 38720108, 2024). "TNFRSF9 is an activation marker for tumor-infiltrating Tregs, and inhibition of TNFRSF9 boosts anti-cancer treatments via reducing the immune suppressive function of Tregs29." (PMID 38589454, 2024). "We demonstrated that higher levels of sCD137 and sTIM3 were significantly associated with the risk of OS, and their corresponding genes TNFRSF9 and HAVCR2 were significantly elevated in tumor tissues." (PMID 38730580, 2024). "SLC7A11 expression was positively associated with the expression of immune checkpoint genes (NRP1, TNFSF4, TNFRSF9, and CD276) and tumour mutation burden." (PMID 37919768, 2023). "Compared to pre-treatment, we observed that tumor cells in TME of post-treatment samples consistently expressed TNFRSF9 at higher level." (PMID 38096229, 2023). "Further investigation revealed that the TNFRSF9+subset within tumor-infiltrating CD4+Treg exhibited potent immunosuppressive abilities." (PMID 38250084, 2023). "Tnfrsf9 (also known as 4-1BB or Cd137) expression has been well-studied in immune cells, but little is known about its function in tumor cells." (PMID 35721518, 2022). "Alongside TNFRSF4/OX40 and TNFRSF9/4-1BB, we selected a number of markers of tumor-resident Tregs (CTLA4, ICOS, TIGIT, and FOXP3) and performed k-means clustering for all UPS, MFS, and DDLS samples in the TCGA." (PMID 35558159, 2022). "We show that TNFRSF9 inhibits tumor progression by suppressing p38 phosphorylation and the protein expression of the downstream target of p-p38 and PAX6." (PMID 35799609, 2022). "Recent research has supported the finding that, as a known activation marker for antigen-specific Tregs, TNFRSF9+ cells also form a major part of the functional tumor Tregs." (PMID 36358653, 2022). "Recently, TNFRSF9 mRNA level was shown to be a robust marker of tumor-infiltrating Tregs that suppress antitumor response." (PMID 35365620, 2022). "Prior studies have shown that utomilumab and urelumab, which are TNFRSF9 agonistic antibodies, can deliver costimulatory signals, enhancing T-cell–mediated anti-tumor activity in vitro and in vivo." (PMID 36157576, 2022). "The immunohistochemical image showed less Bcl-2 expression and more TNFRSF9 expression in the pLV-TNFRSF9 injected tumor." (PMID 35799609, 2022). "The western blot assay result indicates that, in eight matched tumor tissues, the protein expression of TNFRSF9 was significantly promoted with pLV-TNFRSF9 injection." (PMID 35799609, 2022). "The cross-linking of TNFSF9 and TNFRSF9 on liver cancer cells HepG2 triggers the production of interleuukin-8 (IL-8) by tumor cells." (PMID 34517345, 2021). "In summary, TNFRSF9, TNF, and IFNG represent an efficient and effective surrogate combination for a much broader panel of functions associated to tumor-reactivity, and can potentially identify the majority of the tumor-specific reactive TIL repertoire in situ." (PMID 34707600, 2021). "Despite of distinct tumor immune microenvironment across different cancer types, we wonder if the TI-Treg-specific expression level of TNFRSF9 can predict prognosis in other cancer types." (PMID 33598101, 2021).
tumor (continued). "We retrieved TNFRSF9, whose inhibition was reported to increase anti-tumor immunity, among the final candidates for surface marker proteins." (PMID 33598101, 2021). "T cells were engineered to have the ability to attack tumor cells by generating CAR constructs consisting of genes encoding scFv, a co-stimulatory domain (CD28 or TNFRSF9), and CD247 signaling domains for T cell proliferation and activation." (PMID 32050611, 2020). "Various clinical trials have demonstrated that blockade of TNFRSF9 altered the tumor microenvironment and minimized systemic exposure." (PMID 30609841, 2019). "4-1BBL (TNFRSF9/CD137) costimulation of tumor-specific T cells is important for T-cell activation and 4-1BBL transfected DCs elicit more effective responses and enhanced CTL killing of tumor cells, due to increased expression of perforin and IFN-γ." (PMID 26872462, 2016). "41BBL co-stimulation of 41BB (TNFRSF9/CD137) on tumor-specific T cells is important for T-cell proliferation, cytokine production, and activation." (PMID 24829753, 2013). "Our findings suggest that TNFRSF9 + Tregs contribute to immune suppression and may enhance their survival in the tumor microenvironment through activated signaling pathways, potentially modulating immune responses." (PMID 40570022, 2025). "Inhibition of glycolysis or PERK deletion in MDMs reduced these immunosuppressive effects, enhanced T cell infiltration, delayed tumor growth, and improved the effectiveness of 4-1BB (also known as CD137 or TNF receptor superfamily member 9 (TNFRSF9)) based immunotherapy." (PMID 41372991, 2025). "TNFRSF9 has received attention in the field of tumor immunology." (PMID 40599317, 2025). "Additionally, the combined use of TNFRSF9 agonists and PD-L1 inhibitors can activate tumor-specific cytotoxic T cells, thereby improving tumor killing." (PMID 40072746, 2025). "The authors speculated that TNFRSF9 is related to the enhanced immunosuppressive activity of Tregs in the tumor." (PMID 39000552, 2024). "TNFRSF9 has also been identified as a marker for activating tumor-reactive Tregs." (PMID 38903179, 2024). "Compared to the Treg cells in blood or adjacent normal tissue, Tregs in the tumor express higher levels of CTLA4, inducible T cell costimulator (ICOS) and tumor necrosis factor receptor superfamily member 9 (TNFRSF9; encoding 4-1BB), which reflect an activated state." (PMID 37187731, 2023). "Recently, a published study showed that TNFRSF9 agonist combined with PD-L1 could effectively activate and amplify tumor-specific cytotoxic T cells, enhancing tumor control and killing." (PMID 35942287, 2022). "Despite the uncertainty, TNFRSF9 has been found to affect tumor cells." (PMID 35799609, 2022). "Next, we investigated the dysregulation effect of TNFRSF9 in tumor development." (PMID 35799609, 2022). "In other words, CD27, EDA, TNF, TNFRSF12A, TNFRSF13C, and TNFRSF9 expression may also affect the immunotherapy effect on tumours by regulating the expression of immune checkpoint molecules in the tumour microenvironment." (PMID 35392242, 2022). "TNFRSF9 mRNA expression positively correlated also with the frequency of effector and memory tumor infiltrating lymphocytes, while it was inversely correlated with the frequency of naïve tumor infiltrating lymphocytes." (PMID 33530328, 2021). "Notably, for the first time, we demonstrated that TNFRSF9 expression level in the TI-Tregs can predict response to anti-PD-1 immunotherapy in human non-small cell lung cancer (NSCLC), which verifies functional impact of TNFRSF9 in immune–tumor interactions." (PMID 33598101, 2021). "TNFRSF9 was also reported as an activation marker for tumor-reactive Tregs." (PMID 33598101, 2021). "All together, we assumed that CD4+ T cells infiltration may be correlation with APE1 expression, and in particularly TNFRSF9+ Treg which belongs to CD4+ T cells influence prognosis in NSCLC given their biological functions during tumor progression." (PMID 33676448, 2021).
tumor (continued). "However, although TNFRSF9 exerts positive immunomodulatory function on immune cells like macrophages, it can also improve tumor metastasis, and thus, further studies are warranted to explore its molecular basis." (PMID 34367975, 2021). "We found that the low TNFRSF9 expression level in Tregs was associated with enhanced overall survival rate and response to anti-PD-1 immunotherapy in patients with NSCLC, proposing that TNFRSF9 promotes immune suppressive activity of Tregs in tumor." (PMID 33598101, 2021). "TNFRSF9 (also known as 4-1BB) is conducive to T cell activation and augments tumor immunity." (PMID 34970594, 2021). "Notably, all six expression-based markers for human TI-Tregs, TIGIT, TNFRSF9, ICOS, CCR8, CD83, and CCRL2, were ranked within the top 10%, which indicates that they are likely to play major roles in tumor-associated Treg functions." (PMID 33598101, 2021). "4-1BB (TNFRSF9 or CD137) may be considered one of the immune-modulating molecules with contradictory tumor activity." (PMID 32823814, 2020). "Taking CD4+ Treg cells and CD8+ cytotoxic T cells as examples, Treg cells derived from tumor tissues showed higher expression of LAYN, LGALS1 and TNFRSF1B, and cytotoxic T cells derived from tumor tissues showed higher expression of TNFRSF9 (encoding 4-1BB), LAYN and CTLA4." (PMID 36104333, 2022). "A Humabody-based therapeutic that has agonist activity against CD137 (4-1BB, HGNC:TNFRSF9) continent upon expression of prostate-specific membrane antigen in the tumour microenvironment, CB307, has recently begun clinical studies and may provide the first clinical evidence of this hypothesis." (PMID 34969998, 2022). "Therefore, we hypothesised that CD27, EDA, TNF, TNFRSF12A, TNFRSF13C, and TNFRSF9 may affect tumour prognosis mainly by regulating the TGF-β signaling pathway." (PMID 35392242, 2022). "Functional enrichment analysis of genes highly expressed in early‐stage tumours indicated an up‐regulation of tumour necrosis factor signalling pathways in CD8 Trm and TNFRSF9 Treg cells." (PMID 41275425, 2025). "Preclinical results have demonstrated that agonistic antibodies targeting 4-1BB (TNFRSF9) and OX40 (TNFRSF4) can elicit long-term anti-tumor immunity in humanized mouse models." (PMID 39979981, 2025). "Together with the upregulation of the stimulatory immune checkpoint molecules TNFRSF9 and CD70, which occurred after the tumour cells were treated with Pt-Au NPs and exposure to NIR, a higher fraction of apoptotic and necrotic tumour cells occurred." (PMID 40004038, 2025). "IDO1 is positively correlated with CD274, TNFRSF9, TNFRSF4, PDCD1LG2, IDO2, and CD48 in many tumor types." (PMID 38539263, 2024). "Flow cytometry was performed to confirm the MS results on several critical markers of tumor immune responses including CD25 (IL2RA), CD5, CD137 (TNFRSF9), ICOS, PD1 (PDCD1), CTLA4, and CD62L (SELL)." (PMID 38242867, 2024). "In this study, the inflammatory response genes (ITGA5, LCK, GCH1, TNFRSF9 and SLC7A1) play different role in immune tumor microenvironment." (PMID 38903179, 2024). "In T cells, immune stimulation by the tumor led to the up-regulation of many co-stimulatory receptors, including ICOS, TNFRSF18, TNFRSF4, and TNFRSF9/4-1BB." (PMID 39475596, 2024). "Consistent with RNA-seq analysis, Tnfrsf9 was downregulated in both D374Y and PCSK9 tumors but showed increased expression in Q152H tumor." (PMID 36588164, 2023). "This group displayed higher expressions of PD-1, TNFRSF9, and CD86, along with increased enrichment scores for tumor marker pathways, distinguishing them from Cluster A patients." (PMID 38053840, 2023). "qRT-PCR assays were performed to evaluate the mRNA expression of TNFRSF9 and PAX6 in the tumor tissues." (PMID 35799609, 2022). "An exhaustion signature of 28 genes, including TIGIT, TNFRSF9/4-1BB, and CD27, was identified in exhausted T cells in melanoma tumours and was also found to be upregulated in high-exhaustion cells in most tumours." (PMID 36154923, 2022).